AKAP17A (A-kinase anchoring protein 17A )
Synonyms: 721P; AKAP-17A; CCDC133; CXYorf3; DXYS155E; PRKA17A; SFRS17A; XE7; XE7Y
Gene: Protein-coding gene on chromosome Y (1,591,604 to 1,602,532, forward strand). Ensembl gene ENSG00000292343.
Diseases named in the same sentence as AKAP17A in open-access papers:
AKAP17A is named in the same sentence as 3 diseases in open-access papers, as found by Europe PMC text mining. Sharing a sentence is not in itself a finding about the gene and the disease. The quoted sentences say what the papers report.
cognitive decline (2 papers, 2019 to 2024). "We present here evidence to suggest that expression levels of HNRNPM, HNRNPA0 and AKAP17A genes may be associated with cognitive decline, whilst AKAP17A levels may be associated with decline in physical performance in a human population." (PMID 31292793, 2019).
Autoimmunity (1 paper, 2023). The occurrence of an immune reaction against the organism's own cells or tissues. "The only PAR gene that emerged was a variant in AKAP17A (X:1601004:C-G) associated with autoimmunity." (PMID 37800145, 2023).
chronic tic disorder (1 paper, 2018). A neurological disorder presenting in childhood that is characterized by either motor or phonic tics, but not both, that occur daily or nearly daily for at least a year and are not attributed to an identifiable cause. "Both ZBED1 and PPP2R3B may have a role in the regulation of cell growth and division, and AKAP17A has been associated with chronic tic disorder." (PMID 30213969, 2018).